PRDX1 (peroxiredoxin 1)
Diseases named in the same sentence as PRDX1 in open-access papers (continued):
Sharing a sentence is not in itself a finding about the gene and the disease.
cancer (continued). "Generally, considering PRDX1 as a therapeutic target in cancer is not entirely a new idea." (PMID 30287919, 2018). "The function of PRDX1 is not restricted to its antioxidant activities in cancers." (PMID 27653015, 2017). "Furthermore, several studies have demonstrated that the overexpression of PRDX1, PRDX2, and PRDX3 has an important role in many cases of drug resistance and that the therapeutic agents targeting these PRDXs are frequently studied for the treatment of cancer." (PMID 27418953, 2016). "This preliminary data also suggest that the autoantibody against Prdx1 may be used as a potential biomarker in certain types of cancer but not for all types of cancer." (PMID 24009050, 2013). "Levels of PRDX1 and PRDX2 protein were estimated in the urine of 100 cancer patients and 50 non-malignant controls by ELISA." (PMID 35812179, 2022). "Furthermore, genetic targeting of PRDX1 or adenanthin, but not PRDX2, potently sensitised all six cancer cell lines studied, but not the non-cancerous cells, to glucose oxidase and ascorbate." (PMID 30287919, 2018).
infection (21 papers, 2012 to 2025). The state of being infected such as from the introduction of a foreign agent such as serum, vaccine, antigenic substance or organism. "Peroxiredoxin 1 and 2 have been identified to maintain molluscan health through catalysing the interaction between thioredoxin and hydrogen peroxide and are also expressed earlier in resistant strains than susceptible ones following infection." (PMID 31521183, 2019). "Western blotting confirmed these findings at the protein level, with Bacilli infection markedly increasing PRDX1 protein expression, in contrast to the Streptococcaceae-infected and control groups, which showed no substantial difference." (PMID 40693141, 2025). "When averaged across all brain regions, expression of HO-2 and Prdx1 changed significantly during the course of infection." (PMID 32669339, 2020). "We quantified the protein expression of NQO1, GPX1, Prdx1, HO-1, and HO-2 during the course of infection." (PMID 32669339, 2020). "Markers of oxidative stress triggered by the infection resulting in elevated ROS levels were matched by corresponding increases in the levels of antioxidant proteins, such as peroxiredoxin-1 (Prdx1), superoxide dismutase (Sod2), and glutathione S-transferase (Gstm3) in lung tissues." (PMID 36614003, 2022). "Therefore, Prdx1 is likely to be essential for the early stages of infection, such as replication and transcription of the virus genome." (PMID 34207367, 2021). "Additionally, Prdx1 was also involved in host defense against infection from microorganisms inducing Interleukin 12 (IL-12) and Nitric Oxide (NO) production." (PMID 30521599, 2018). "The differential regulation of PRDX1 by motif 29-DEMI-32 and motif 39-KEALSDGI-46 may lead to different inflammatory and stress responses to WT, Mut-1, and Mut-2 infections, as PRDX1 is an important regulator in these responses." (PMID 29207503, 2017). "Thus, PRDX1 was knocked down in HCT116 and SW620 cells by lentiviral infection to generate the stable cell lines (HCT116PRDX1-KD and SW620PRDX1-KD), while PRDX1 was overexpressed in SW480 cells to generate SW480PRDX1-OE stable cells." (PMID 39430237, 2024). "Consistent with a central role for oxidative stress responses in cell-intrinsic responses to infection, key antioxidant enzymes (GSR, CAT, GPX1, and PRDX1) were downregulated by YFV-17D and select genes (SOD2, NFE2L2, and KEAP1) were upregulated by MnTBAP treatment." (PMID 39282299, 2024). "Sod1 and Prdx1 were not significantly affected by infection, while interestingly Hmox1 expression was increased at 2 dpi." (PMID 37022178, 2023). "It is worth mentioning that since the Prdx1-Exosc5 complex also exists in HBV uninfected cells, this peroxiredoxin could also play antiviral activity in the case of other infections." (PMID 34207367, 2021). "This appears to be highly specific, since amounts of PRDX1-4 or PRDX2 did not change during infection (lane 5–8)." (PMID 23210548, 2012). "In contrast, Streptococcaceae infection did not significantly alter PRDX1 fluorescence intensity." (PMID 40693141, 2025). "Overall, CMA3p20 infection of BALB/c mice caused a significant decrease in the expression of the AOE genes in the lung tissue, specifically Cat, Gstm1, and Prdx6, while it did not affect Sod1 and Prdx1." (PMID 37022178, 2023). "We found that WT infection did not affect the nuclear presence of PRDX1." (PMID 29207503, 2017).
bacterial infection (5 papers, 2015 to 2025). "To further elucidate the interactions among specific bacterial infections, PRDX1 expression, glycolysis, and immunotherapeutic response, we conducted both in vitro and in vivo studies using Huh7 cells." (PMID 40693141, 2025). "It suggests that Bacillus cereus PAS38 may promote lymphocytes production of PRDX1 in immune organs, so as to improve the ability of organism to deal with bacterial infection." (PMID 32609751, 2020). "Combined with the results of this experiment, it is suggested that PRDX1 may play a role in the resistance of chickens to bacterial infection through the activation of immune signals." (PMID 32609751, 2020).
cardiovascular diseases (4 papers, 2017 to 2025). "Notably, increasing evidence has shown that Prdx1 plays important roles in various cardiovascular diseases." (PMID 32802259, 2020). "Thioredoxin system is composed of the anti‐oxidant thioredoxin‐1 (TXN1), thioredoxin reductase (TXNRD1), thioredoxin peroxidase‐1 (PRDX1), and the pro‐oxidant thioredoxin‐interacting protein (TXINP), which functions as a crucial defense mechanism against oxidative damage in cardiovascular diseases." (PMID 32618439, 2020).
adenocarcinoma (3 papers, 2012 to 2024). A common cancer characterized by the presence of malignant glandular cells. "Representative images of Hematoxylin-eosin (HE) staining revealed that AOM/DSS-treated WT mice exhibited large adenocarcinomas with disordered crypt structure and glandular lumens, a phenotype that was attenuated in PRDX1-KO mice." (PMID 39430237, 2024).
colonic polyps (1 paper, 2024). "Fer-1 significantly rescued the suppressive effects of PRDX1 knockout on the growth of colonic polyps by inhibiting ferroptosis through activating NRF2-GPX4 signalling pathway." (PMID 39430237, 2024).
infectious disease (1 paper, 2017). A disorder directly resulting from the presence and activity of a microbial, viral, or parasitic agent in humans. "Another motif-specific regulatory target was PRDX1 (peroxiredoxin 1), a molecule predicted by IPA to be involved in 17 biological functions including free radical scavenging, inflammatory diseases, and infectious diseases." (PMID 29207503, 2017).
PRDX1 also shares sentences with these, for which no sentence is quoted: anthrax (9 papers); myocardial infarction (4); haemolytic anaemia (3); inflammation (3); lung adenocarcinoma (3); acute pancreatitis (2); anaplastic thyroid cancer (2); Clear Cell Renal Cell Carcinoma (2); irritable bowel syndrome (2); islet cell adenomas (2); malaria (2); neurological disease (2); pancreatic adenocarcinoma (2); rectal cancer (2); rheumatoid arthritis (2); steatosis (2); abdominal aortic aneurysm (1); acute kidney injury (1); acute lung injury (1); acute lymphoblastic leukemia (1); acute myocardial infarction (1); age (1); age-related macular degeneration (1); alcoholic fatty liver disease (1); Alzheimer disease (1); amoebiasis (1); anemia (1); arteriosclerosis (1); asthma (1); astrocytoma (1).
A further 57 diseases each share a sentence with PRDX1 in 1 paper.